FAM157C (family with sequence similarity 157 member C)
Synonyms: LINC02193
Gene: Long non-coding RNA gene on chromosome 16 (90,101,034 to 90,222,852, forward strand). Ensembl gene ENSG00000260528.
Diseases named in the same sentence as FAM157C in open-access papers:
FAM157C is named in the same sentence as 1 disease in open-access papers, as found by Europe PMC text mining. Sharing a sentence is not in itself a finding about the gene and the disease. The quoted sentences say what the papers report.
Sepsis (1 paper, 2022). Sepsis is defined as life-threatening organ dysfunction caused by a dysregulated host response to infection. "There were five lncRNAs in the network, including PCED1B-AS1, SATB1-AS1 and LINC01422 down-regulated, BACH1-IT2 and FAM157C up-regulated, but what role these lncRNAs in the progression of sepsis is not clear." (PMID 36457745, 2022).